PGBD5 (piggyBac transposable element derived 5)
Description:
Transposase that mediates sequence-specific genomic rearrangements. Can induce genomic rearrangements that inactivate the HPRT1 gene.
Synonyms: DKFZp761A0620; FLJ11413; NEDSHS
Tractability: PROTAC: ubiquitination databases record sites on it; its protein half-life has been measured.
Gene: Protein-coding gene on chromosome 1 (230,314,490 to 230,426,332, reverse strand). Ensembl gene ENSG00000177614.
Subcellular location: Nucleus
Subcellular location (Human Protein Atlas): Nucleoplasm
Gene Ontology:
Molecular function: transposase activity
Biological process: non-replicative DNA transposition
Cellular component: nucleoplasm; nucleus
Genetic constraint (gnomAD): Loss-of-function variants: 12 observed, 43.8 expected, observed/expected ratio (o/e) 0.27, 90% interval 0.17 to 0.44. The upper end of that interval is the gene's LOEUF score, 0.44, which puts it in group 1 of 6, group 1 being the genes least tolerant of losing a copy. Missense variants: 630 observed, 708.93 expected, observed/expected ratio (o/e) 0.89, 90% interval 0.83 to 0.95. Synonymous variants: 313 observed, 305.05 expected, observed/expected ratio (o/e) 1.03, 90% interval 0.94 to 1.13.
Homologues: Orthologues: chimpanzee PGBD5 (99% identical), macaque PGBD5 (99% identical), rabbit PGBD5 (96% identical), dog PGBD5 (94% identical), rat Pgbd5 (94% identical), pig PGBD5 (93% identical), mouse Pgbd5 (93% identical), guinea pig PGBD5 (91% identical), tropical clawed frog pgbd5 (78% identical), zebrafish pgbd5 (74% identical).
Diseases named in the same sentence as PGBD5 in open-access papers:
PGBD5 is named in the same sentence as 19 diseases in open-access papers, as found by Europe PMC text mining. Sharing a sentence is not in itself a finding about the gene and the disease. The quoted sentences say what the papers report.
Anxiety (1 paper, 2026). Intense feelings of nervousness, tension, or panic often arise in response to interpersonal stresses. "Both female and male Pgbd5−/− mice traveled longer distances in the open maze arms (normalized to total distance traveled) compared to their WT littermates, indicating reduced avoidance of the anxiogenic open arm of the EPM, consistent with reduced anxiety-like behavior (ANOVA P = 2.7 × 10−6)." (PMID 41533792, 2026).
Ataxia (1 paper, 2026). Ataxia refers to impaired coordination of voluntary muscle movement. "While additional patients will be needed to define the full spectrum of human PGBD5 deficiency syndrome, these findings indicate that PGBD5 mutations are associated with developmental delay, intellectual disability, ataxia-dystonia, and epilepsy." (PMID 41533792, 2026). "At least in part, this may explain the phenotype of human PGBD5 deficiency, including developmental delay, intellectual disability, ataxia-dystonia, and in particular epilepsy, given the importance of an imbalance in excitatory and inhibitory neuronal activity in seizure disorders." (PMID 41533792, 2026).
developmental delay (1 paper, 2026). "Its genetic inactivation constitutes the PGBD5 deficiency disorder, characterized by developmental delay, intellectual disability, language and motor impairments, seizures, and reductions in corpus callosum and cerebellar size." (PMID 41533792, 2026).
epilepsy (1 paper, 2026). A brain disorder characterized by episodes of abnormally increased neuronal discharge resulting in transient episodes of sensory or motor neurological dysfunction, or psychic dysfunction. "Here, we show that PGBD5 contributes to normal brain development in mice and humans, and its deficiency causes disorder of intellectual disability, movement disorders, and epilepsy." (PMID 41533792, 2026).
invasive breast carcinoma (1 paper, 2022). A carcinoma that infiltrates the breast parenchyma. "In addition, a multiomics analysis showed that PGBD5 amplification was associated with poorer overall survival in lobular ductal types of invasive breast cancer." (PMID 36211409, 2022).
pelvic organ prolapse (1 paper, 2017). Abnormal descent of a pelvic organ resulting in the protrusion of the organ beyond its normal anatomical confines. "Intriguingly, our previous GWAS investigation of pelvic organ prolapse using African American and Hispanic women identified a common marker across those populations near gene PGBD5 in the 1q42.1–3 region." (PMID 28582460, 2017).
rhabdoid tumor (1 paper, 2020). An aggressive malignant embryonal neoplasm usually occurring during childhood. "In rhabdoid tumors, which are thought to be derived from developing neuroectodermal progenitor cells, PGBD5 promotes somatic sequence-specific genomic rearrangements, some of which cause inactivating mutations of tumor suppressor genes." (PMID 32411637, 2020). "Remarkably, many solid tumors of children and young adults, including medulloblastomas, neuroblastomas, ependymomas, Ewing sarcomas, and rhabdoid tumors, express PGBD5, which is enzymatically related to RAG1/2." (PMID 32411637, 2020).
rhabdomyosarcoma (1 paper, 2022). A rare aggressive malignant mesenchymal neoplasm arising from skeletal muscle. "It has been reported that in rhabdomyosarcoma cells PGBD5 is physically linked to genome-specific signal sequences that promote the induction of DNA rearrangements." (PMID 36211409, 2022).
cancer (4 papers, 2014 to 2022). A tumor composed of atypical neoplastic, often pleomorphic cells that invade other tissues. "Their developmental functions can explain the early-onset of RAG1/2 and PGBD5-expressing cancers, but can also promote mutations in older individuals, simply at reduced relative incidence." (PMID 32411637, 2020). "In our hypothesis, mutations induced by developmental mutators such as RAG1/2 and PGBD5 that happen early in life lead to specific forms of somatic mosaicism and the risk of early onset cancers." (PMID 32411637, 2020). "Finally, given the potentially mutagenic activity of active DNA transposases, we anticipate that unlicensed activity of PGBD5 and other domesticated transposases can be pathogenic in specific disease states, particularly in cases of aberrant chromatin accessibility, such as cancer." (PMID 26406119, 2015). "Moreover, we implicate several of these gene hits not only in ccRCC for the first time (BHLHB3, CAMK1, CDH13, ENPP3, KCNJ2, KSR1, PLOD2, and TCF8), but also in a cancer model for the first time (CEP290, EFCAB3, PGBD5, RAPGEF5, SSPN, and TOX2)." (PMID 24979721, 2014).
tumor (3 papers, 2020 to 2025). "We showed that EZH2 inhibition promotes DNA damage in epithelioid and rhabdoid tumor cells, at least in part via its induction of piggyBac transposable element derived 5 (PGBD5)." (PMID 40794452, 2025). "This is consistent with the findings of PGBD5 in other tumours." (PMID 36211409, 2022).
blood cancers (1 paper, 2026). "In the case of RAG1/2 and PGBD5, their dysregulation causes somatic oncogenic DNA rearrangements in blood cancers and solid tumors affecting children and young adults." (PMID 41533792, 2026).
neurodevelopmental disorder (1 paper, 2026). A behavioral and cognitive disorder with onset during the developmental period that involves impaired or aberrant development of intellectual, motor, or social functions. "Thus, dysregulation of PGBD5 functions during brain development may also contribute to the somatic DNA rearrangements in specific neurodevelopmental disorders." (PMID 41533792, 2026).
PGBD5 also shares sentences with these, for which no sentence is quoted: breast carcinoma (1 paper); Dystonia (1); glioblastoma (1); Intellectual disability (1); movement disorder (1); papillary thyroid cancer (1); sarcoma (1).